EIF2D (eukaryotic translation initiation factor 2D)
Description:
Translation initiation factor that is able to deliver tRNA to the P-site of the eukaryotic ribosome in a GTP-independent manner. The binding of Met-tRNA(I) occurs after the AUG codon finds its position in the P-site of 40S ribosomes, the situation that takes place during initiation complex formation on some specific RNAs. Its activity in tRNA binding with 40S subunits does not require the presence of the aminoacyl moiety. Possesses the unique ability to deliver non-Met (elongator) tRNAs into the P-site of the 40S subunit. In addition to its role in initiation, can promote release of deacylated tRNA and mRNA from recycled 40S subunits following ABCE1-mediated dissociation of post-termination ribosomal complexes into subunits.
Synonyms: HCA56; LGTN
Tractability: PROTAC: ubiquitination databases record sites on it; its protein half-life has been measured.
Gene: Protein-coding gene on chromosome 1 (206,571,292 to 206,612,514, reverse strand). Ensembl gene ENSG00000143486.
Subcellular location: Cytoplasm
Subcellular location (Human Protein Atlas): Cytosol; Nuclear bodies
Gene Ontology:
Molecular function: translation initiation factor activity; signaling receptor activity; RNA binding
Biological process: formation of translation preinitiation complex; IRES-dependent viral translational initiation; ribosome disassembly; intracellular protein transport; protein-containing complex organization; translational initiation
Cellular component: cytoplasm; cytosol
Genetic constraint (gnomAD): Loss-of-function variants: 54 observed, 78.61 expected, observed/expected ratio (o/e) 0.69, 90% interval 0.55 to 0.86. The upper end of that interval is the gene's LOEUF score, 0.86, which puts it in group 3 of 6, group 1 being the genes least tolerant of losing a copy. Missense variants: 569 observed, 735.85 expected, observed/expected ratio (o/e) 0.77, 90% interval 0.72 to 0.83. Synonymous variants: 229 observed, 283.54 expected, observed/expected ratio (o/e) 0.81, 90% interval 0.72 to 0.9.
Homologues: Orthologues: chimpanzee EIF2D (99% identical), macaque EIF2D (98% identical), pig EIF2D (89% identical), rabbit EIF2D (85% identical), guinea pig EIF2D (83% identical), rat Eif2d (81% identical), mouse Eif2d (81% identical), dog EIF2D (77% identical), tropical clawed frog eif2d (57% identical), zebrafish eif2d (57% identical), Drosophila melanogaster eIF2D (35% identical), Caenorhabditis elegans eif-2D (29% identical).
Diseases named in the same sentence as EIF2D in open-access papers:
EIF2D is named in the same sentence as 10 diseases in open-access papers, as found by Europe PMC text mining. Sharing a sentence is not in itself a finding about the gene and the disease. The quoted sentences say what the papers report.
hepatocellular carcinoma (2 papers, 2015 to 2018). A malignant tumor that arises from hepatocytes. "Our present findings in human cells clearly demonstrate that neither eIF2A nor eIF2D are involved in protein synthesis directed by HCV IRES, and are in accord with a recent result demonstrating that knockdown of eIF2A or eIF2D in hepatoma cells has little effect on HCV IRES-driven translation." (PMID 29487587, 2018). "There is no available literature on the possible involvement of eIF2D in cancer with the exception of eIF2D being identified as a hepatocellular carcinoma (HCC) – associated antigen in a study of four HCC patients." (PMID 26636041, 2015).
fibrosarcoma (1 paper, 2020). A malignant mesenchymal fibroblastic neoplasm affecting the soft tissue and bone. "Knockdown of DENR and/or eIF2D also reduced ATF4 protein levels in HT1080 fibrosarcoma cells indicating this is not specific to HeLa cells." (PMID 32938922, 2020).
retinal degeneration (1 paper, 2020). Degeneration of the retina. "The accelerated retinal degeneration phenotype of eIF2D mutants is similar to that observed in perk mutants, albeit less severe, likely due to the presence of DENR–MCTS1." (PMID 32938929, 2020). "In addition, eIF2D and DENR mutants are more vulnerable to amino acid deprivation and susceptible to age-dependent retinal degeneration in a Drosophila model of Retinitis Pigmentosa." (PMID 32938929, 2020). "We next examined if eIF2D affects retinal degeneration in the ninaEG69D model." (PMID 32938929, 2020).
viral infection (1 paper, 2023). "It has been suggested that, upon viral infection, translation can be switched from the standard 5 ́cap dependent mechanism to one using non-AUG codons facilitated by eIF2A and/or eIF2D." (PMID 38023930, 2023).
infection (3 papers, 2017 to 2023). The state of being infected such as from the introduction of a foreign agent such as serum, vaccine, antigenic substance or organism. "The loss of eIF2A or eIF2D essentially prevents replication of PV requiring a longer infection time." (PMID 36689548, 2023). "This tool permitted us to compare outcomes for transfection or infection in the absence or presence of eIF2A or eIF2D." (PMID 36689548, 2023). "In the presence of eIF2A and eIF2D, PV establishes infection faster, replicates to higher levels, and replicates faster than in the absence of one of these factors." (PMID 36689548, 2023). "Moreover, silencing of eIF2A or eIF2D by transfection of the corresponding siRNAs in HAP1 WT, HAP1-eIF2A− and HAP1-eIF2D− cells had little effect on the synthesis of viral proteins late in infection." (PMID 28240315, 2017). "While population-level studies only revealed a role for eIF2A and eIF2D when in vitro transcribed RNA was transfected into cells to initiate infection and/or recombination, studies at the single-cell level suggested a role for these factors during normal, virus-initiated infection." (PMID 36689548, 2023). "We did not observe a strong dependence on eIF2A and/or eIF2D when infection was launched using virus." (PMID 36689548, 2023). "We conclude that the IRES-independent, eIF2A/eIF2D-dependent mechanism likely functions during normal infection when certain factors are present or not in the host cell." (PMID 36689548, 2023). "In contrast, introduction of the nanoLuc reporter by infection did not exhibit a significant dependence of either eIF2A or eIF2D." (PMID 36689548, 2023). "First, infections that required longer than 5 hours for completion appeared to be lost in the absence of eIF2A or eIF2D." (PMID 36689548, 2023). "Second, 25% of the cells appeared recalcitrant to infection in the absence of eIF2A or eIF2D." (PMID 36689548, 2023). "One-quarter of cells exposed to PV do not establish infection in the absence of eIF2A or eIF2D." (PMID 36689548, 2023).
tumor (2 papers, 2017 to 2021). "In TCGA BRCA tumor samples, the gene expression levels of EIF2D positively correlate with its copy number levels as a result of the frequent amplification events of chromosome 1q." (PMID 29259170, 2017).
EIF2D also shares sentences with these, for which no sentence is quoted: cancer (2 papers); autosomal dominant retinitis pigmentosa (1); neurodegenerative disease (1); pancreatic tumor (1).